ENSG00000276509 (novel transcript)
Synonyms: LOC105371254
Gene: Long non-coding RNA gene on chromosome 1 (146,229,086 to 146,376,495, forward strand). Ensembl gene ENSG00000276509.
Gene Ontology:
Molecular function: triplet codon-amino acid adaptor activity
Biological process: translation